MIR940 (microRNA 940)
Synonyms: hsa-mir-940; MIRN940; mir-940
Gene: MicroRNA gene on chromosome 16 (2,271,747 to 2,271,840, forward strand). Ensembl gene ENSG00000284346.
Gene Ontology:
Biological process: miRNA-mediated post-transcriptional gene silencing
Cellular component: RISC complex
Homologues: Orthologues: macaque mml-mir-940 (99% identical), chimpanzee ptr-mir-940 (98% identical).